TLR9 (toll like receptor 9)
Diseases named in the same sentence as TLR9 in open-access papers (continued):
Sharing a sentence is not in itself a finding about the gene and the disease.
cerebral malaria (8 papers, 2012 to 2020). A sequestration of Plasmodium falciparum in the brain, which can cause coma and/or seizures. "Further report indicates that two TLR9 SNPs (TLR9 C allele at -1237 and G allele at 1174) are associated with increase in IFNγ levels in children with cerebral malaria." (PMID 32944216, 2020). "In the studies that have reported a protective effect of TLR9 disruption, cerebral malaria was still more severe than that observed in MYD88-deficient mice, suggestive of signalling contributions from other MYD88-dependent pathways." (PMID 25192715, 2014). "berghei’ hereafter) infection of the C57BL/6 mouse, in which Type I inflammation promotes a lethal infection with neurological symptoms consistent with cerebral malaria, a deficiency in either TLR9 or MYD88 partially protects against lethal disease." (PMID 25192715, 2014). "Studies have demonstrated that TLR9-deficient mice survived more during cerebral malaria and that the antagonist-mediated TLR9 inhibition conferred protection against cerebral malaria in mice." (PMID 23316245, 2012). "Another study showed higher serum Interferon gamma levels in children carrying the TLR9-1237-C allele with cerebral malaria, indicating that enhanced TLR9 mediated immune responses are also relevant inside the CNS." (PMID 22577991, 2012). "As expected, treatment with E6446, a synthetic antagonist of nucleic-acid-sensing TLRs, was reported to minimize the activation of TLR9 and stopped the exacerbated cytokine response during cerebral malaria." (PMID 32944216, 2020). "Therapy with E6446, a synthetic antagonist of nucleic-acid-sensing TLRs, was reported to diminish the activation of TLR9 and prevented the exacerbated cytokine response during cerebral malaria and the signs of ECM were prevented." (PMID 29495555, 2018). "As expected, Tlr7-/-Tlr9-/- mice demonstrated improved survival as compared to wild-type mice, with 24% escaping cerebral malaria." (PMID 25192715, 2014). "The loss of both TLR7 and TLR9 signalling leads to cytokine dysregulation during the course of P. berghei ANKA infection and protects against symptoms of cerebral malaria." (PMID 25192715, 2014). "In animal studies, it has been demonstrated that mice deficient in TLR9 survived cerebral malaria better than the wild type mice and inhibition of TLR9 activations by TLR9 agonist conferred protection against cerebral malaria in mice." (PMID 22594374, 2012). "Another study on TLR9 -1237 SNPs showed higher serum Interferon gamma levels in children with cerebral malaria, indicating that enhanced TLR9 mediated immune responses are also relevant inside the CNS." (PMID 22662111, 2012). "In addition to a potential direct role of TLR9 in the pathogenesis of cerebral malaria, a hyperresponsiveness of TLR9 in experimentally infected rodents was observed." (PMID 29495555, 2018). "The simplest interpretation of these data is that TLR7 and TLR9 synergistically signal to promote cerebral malaria, with both sensors being required for full elaboration of lethal pathology (and conversely, loss of both sensors not conferring more protection than loss of either sensor alone)." (PMID 25192715, 2014). "However, in contrast to findings with TLR9- and MYD88-deficient mice, in the only study to examine the role of TLR7-deficiency in cerebral malaria, TLR7 was found to be irrelevant for precipitation of fatal disease." (PMID 25192715, 2014). "Importantly, unlike the synergistic interaction between TLR7 and TLR9 suggested by the survival data, these results are consistent with a model in which TLR7 and TLR9 signal redundantly through MYD88 to promote cytokine production during experimental cerebral malaria." (PMID 25192715, 2014).
cutaneous leishmaniasis (8 papers, 2012 to 2025). Leishmaniasis affecting the skin. "More recently, the formulation of a defined polyprotein anti-Leishmania vaccine candidate in conjunction with TLR4 or TLR9 agonists was evaluated as an immunotherapeutical treatment in a mouse model of cutaneous leishmaniasis." (PMID 22523644, 2012). "Previous in vivo studies using mouse models of visceral and cutaneous leishmaniasis have reported that, during the early phase of infection, DCs can activate NK cells in a TLR9 and IL-12-dependent manner, thereby limiting parasite spread and preventing disease establishment." (PMID 39963187, 2025). "TLR9 belongs to the pathogen recognition receptors, interacting with intracellular parasites such as Leishmania, and it is crucial for the induction of NK cells through the innate immune response in cutaneous leishmaniasis." (PMID 35167596, 2022). "Moreover, monocytes from patients with cutaneous leishmaniasis due to L. braziliensis infection display a high expression of TLR9, suggesting a role for this molecule in active disease." (PMID 29358935, 2017). "For cutaneous leishmaniasis, the lipopeptide adjuvants Pam2 and Pam3 were compared to that of the Th1-driving double-stranded DNA TLR9 agonist CpG for their ability to improve the efficacy of the autoclaved Leishmania major (ALM) vaccine to protect against L. major infection." (PMID 26897363, 2016). "Finally, Cpg ODN improved the clinical outcome of immunized rhesus macaques infected with L. major, supporting the hypothesis that TLR9 stimulation might improve the efficacy of vaccination against cutaneous leishmaniasis." (PMID 22523644, 2012).
esophageal cancer (8 papers, 2013 to 2025). A primary or metastatic malignant neoplasm involving the esophagus. "In esophageal cancer, TLR9 expression is associated with aggressiveness and tumor grades." (PMID 38390872, 2024). "For example, in esophageal cancer, increased expression of TLR3, TLR4, TLR7, and TLR9 has been linked to esophageal squamous cell carcinomas, while TLR1, TLR2, TLR4, and TLR6 are often overexpressed in esophageal adenocarcinoma." (PMID 40109582, 2025). "Moreover, patients with esophageal cancer and lymph node metastases had higher TLR-4 levels in tumor tissues, and in the subgroup with esophageal-gastric junction adenocarcinoma, significantly higher expression of TLR-7 mRNA and TLR-4, TLR-7, and TLR-9 proteins was observed." (PMID 39451226, 2024).
fungal infections (8 papers, 2013 to 2025). "In recent years, the role of intracellular pattern recognition receptors (TLR3, TLR7, TLR8, and TLR9) has become increasingly important in the pathophysiology of some mycoses, such as paracoccidioidomycosis, cryptococcosis, aspergillosis, and candidiasis." (PMID 37233274, 2023). "A few studies have previously reported that TLR9 activation plays a crucial role in opportunistic mycoses through models of infection with C. albicans and C. neoformans." (PMID 33446850, 2021). "In recent years, the role of intracellular pattern recognition receptors (TLR3, TLR7, TLR8, and TLR9) has become increasingly important in the pathophysiology of some mycoses, as paracoccidioidomycosis, cryptococcosis, aspergillosis, and candidiasis." (PMID 33194839, 2020). "Among the studied fungal infections, TLR9 activation was related to DNA from A. fumigattus, C. albicans, P. brasiliensis, S. cerevise, M. furfur, and C. neoformans." (PMID 33194839, 2020). "In this section, we will discuss the role of TLR3, TLR7, and TLR9 in the main fungal infections, such as candidiasis, aspergillosis, paracoccidioidomycosis, cryptococcosis, and histoplasmosis." (PMID 33194839, 2020). "A role of Syk in TLR9 signaling has previously been described in fungal infection." (PMID 40980882, 2025). "However, it remains unclear whether this mechanism serves as an immune evasion strategy, with TLR9 acting as an immune response inhibitor, or whether TLR9 targeting to the phagosome is essential for fungal infection control." (PMID 40460068, 2025). "Although type I IFN production via TLR9 activation is well described, IFN-α/β production through alternative pathways and the role of these cytokines in fungal infections remain to be fully elucidated." (PMID 40460068, 2025). "However, a role for TLR9 during P. brasiliensis infection has only been addressed in the context of vaccination, despite the evidences for the involvement of this TLR in other fungal infections." (PMID 23936560, 2013).
leukemia (8 papers, 2011 to 2023). A malignant (clonal) hematologic disorder, involving hematopoietic stem cells and characterized by the presence of primitive or atypical myeloid or lymphoid cells in the bone marrow and the blood. "TLR9 stimulation induced long-term control of preleukemia and established leukemia in the same Eμ-ret model." (PMID 35201533, 2022). "Further studies are necessary to elucidate the role of the TLR1, TLR4, TLR5, TLR6, TLR9, and CD14 polymorphisms in the pathogenesis of leukemia." (PMID 36071076, 2022). "Some of the genes are enriched in a single cell population; for instance, TLR9, a factor whose expression influences the prognosis of leukemia, is found predominantly in the LLin+ cells, and appears to be regulated by Kon." (PMID 27551778, 2016). "In agreement with our results, TLR-9 agonist administration has been shown to induce anti-leukemia responses in mouse models." (PMID 26320191, 2015). "Hence, another potential consequence of ox-mtDNA/TLR9 targeting is to therapeutically prevent the evolution towards leukemia." (PMID 36835307, 2023). "Furthermore, treatment of ALL-bearing mice with CpG ODN, an agonist for TLR9, induced significant immune-mediated killing of human leukemia cells and achieved durable T cell-dependent protection against outgrowth of transplanted syngeneic B-ALL cell lines." (PMID 32015298, 2020).
neuroblastoma (8 papers, 2011 to 2024). Neuroblastoma (NB) is the most common solid, extracranial childhood tumor. "Moreover, TLR9 activity enhances apoptosis of neuroblastoma cells and inhibits the angiogenesis in renal cell carcinoma." (PMID 32012718, 2020). "In addition, TLR9 inhibition has been shown to inhibit tumor growth and apoptosis in neuroblastoma." (PMID 38390872, 2024). "We recently also proved that fentanyl induced HIV replication and chemokine co-receptor expression in human neuroblastoma cell line SH-SY5Y, resulting in decrease in TLR9 expression." (PMID 37113007, 2023). "A classified ‘cold’ neuroblastoma tumor achieved complete tumor eradication upon immune stimulation with anti-CTLA-4, anti-CD40, and toll-like receptor 9 (TLR9) agonist in addition to radiation and anti-GD2-IL-2." (PMID 33803078, 2021). "Based on the lymphodepleting effects of cyclophosphamide, we hypothesized that cyclophosphamide would synergize with the TLR9 agonist, CpG oligodeoxynucleotide (ODN), to produce a T cell-mediated anti-neuroblastoma effect." (PMID 26082836, 2015).
renal cell carcinoma (8 papers, 2011 to 2024). "For example, high TLR9 expression indicated worse prognosis in oesophageal adenocarcinoma, but was associated with better survival in renal cell carcinoma." (PMID 32174922, 2020). "The aim of this study was to examine the expression of TLR9 in renal cell carcinoma (RCC), which is generally renowned of its immunogenic nature." (PMID 21929816, 2011). "TLR9 mRNA and protein are also widely expressed in various human cancer-cell lines as well as in clinical cancer specimens, including breast, prostate, brain, gastric, renal cell carcinoma, and esophageal tumors." (PMID 25101078, 2014). "Therefore, understanding the mechanism on why tumor TLR9 expression levels remain low despite hypoxia in some TNBCs might open novel therapeutic possibilities that might also apply to renal cell carcinoma." (PMID 25101078, 2014). "TLR9 expression has indeed been detected in the nuclei of renal cell carcinoma tumor samples, but whether or not it can directly affect gene expression, requires further experimenting." (PMID 25101078, 2014).
systemic sclerosis (8 papers, 2019 to 2025). A chronic disorder, possibly autoimmune, marked by excessive production of collagen which results in hardening and thickening of body tissues. "In patients with systemic sclerosis (SSc), the intrinsic hyperactivation of TLR9 in B cells contributes to immune dysregulation." (PMID 41293166, 2025). "Those complexes, which are present in blood and tissues from patients suffering from systemic sclerosis (SSc), are DNA-size-dependent and activate plasmacytoid dendritic cells in a TLR9-dependent but CXCR3-independent manner." (PMID 37446102, 2023). "Here the authors show a CXCR3-independent function of CXCL4: it forms liquid crystals with DNA, potentiating mammalian and bacterial DNA recognition by TLR9, thereby amplifying interferon-a production in systemic sclerosis." (PMID 31043596, 2019). "TLR9 function is impaired and the regulation of the early B cell tolerance checkpoint is defective in SLE and systemic sclerosis (SSc) patients." (PMID 36405752, 2022).
acute lymphoblastic leukemia (7 papers, 2013 to 2025). Leukemia with an acute onset, characterized by the presence of lymphoblasts in the bone marrow and the peripheral blood. "In our study, TLR6 C > T rs5743810 and TLR9 C > T r5743836 polymorphisms seem to be a risk for developing acute lymphoblastic leukemia." (PMID 36071076, 2022). "Our study demonstrated that TLR6 C > T rs5743810 and TLR9 C > T rs5743836 polymorphisms are associated with the risk of acute lymphoblastic leukemia and TLR1 T > G rs5743618 and TLR9 C > T rs5743810 is involved with death." (PMID 36071076, 2022). "In pediatrics, a key milestone is a phase I clinical trial of a TLR9 agonist (GNKG168) in children with acute lymphoblastic leukemia (ALL) with minimal residual disease." (PMID 41369391, 2025). "Another phase I trial (NCT01743807) tested the oligonucleotide GNKG163, which acts as a TLR9 agonist, in acute lymphoblastic leukemia (ALL) and AML with MRD, but the trial was terminated." (PMID 29181334, 2017). "As the most common pediatric malignancy, the B-cell precursor acute lymphoblastic leukemia (BCPALL) expresses detectable alterations in costimulatory molecule expression of TLR2, TLR7, and TLR9, being TLR2 ligands PAM3CSK4 and PGN, the most powerful effect on anti-ALL immune responses." (PMID 37822929, 2023).
bronchiolitis (7 papers, 2016 to 2025). Inflammation of the bronchioles characterized by swelling of the bronchioles and mucus accumulation. "In our present study, the TLR9 rs187084 polymorphism was associated with repeated post-bronchiolitis wheezing." (PMID 27498757, 2016). "Former bronchiolitis patients with the homozygous variant TLR9 rs187084 genotype CC had repeated wheezing more often (30.5%, p = 0.02) than children with the wild-type genotype TT (12.2%) during the follow-up period until the age of 1.5 years." (PMID 27498757, 2016). "The main result was that the TLR9 rs187084 polymorphism was associated with repeated wheezing until the age of 1.5 years after bronchiolitis at age less than 6 months." (PMID 27498757, 2016). "This genetic link is further supported by studies on bronchiolitis-induced wheezing, which suggest that the TLR9 rs187084 gene polymorphism may be a potential genetic factor in its occurrence and development." (PMID 40672946, 2025). "Furthermore, SNPs in Toll-like receptors (TLRs), including rs4986790*TLR4, rs1898830*TLR2, rs7656411*TLR2, rs352162*TLR9, and rs187084*TLR9 as well as rs2280788*CCL5 were associated with severity of bronchiolitis." (PMID 32375305, 2020). "TLR9 rs187084 gene polymorphism may be associated with post-bronchiolitis wheezing, and TLR10 rs4129009 gene polymorphism may be associated with atopy." (PMID 27498757, 2016). "In conclusion, we found preliminary evidence that TLR9 polymorphisms may be associated with post-bronchiolitis wheezing." (PMID 27498757, 2016). "Our study was an exploratory study on the possible association between the TLR7 rs179008, TLR8 rs4207992, TLR9 rs187084 or TLR10 rs4219009 gene polymorphisms and characteristics of bronchiolitis in early infancy or post-bronchiolitis outcomes." (PMID 27498757, 2016). "A total of 21 days after C. gattii infection, TLR9-deficient mice had a large number of PMN cells on the mixed inflammatory infiltrate, as well as close to the vessel wall (lumen) and bronchioles—indicating bronchiolitis." (PMID 36145419, 2022). "The aim of the present study was to complement this exploratory study series by evaluating whether the TLR7 rs179008, TLR8 rs2407992, TLR9 rs187084 and TLR10 rs4129009 polymorphisms are associated with the presence, clinical characteristics and viral etiology of bronchiolitis in early infancy." (PMID 27498757, 2016). "The aim of this exploratory study was to evaluate whether there are associations between TLR7 rs179008, TLR8 rs2407992, TLR9 rs187084 or TLR10 rs4129009 polymorphisms and viral findings, clinical characteristics or subsequent wheezing in infants with bronchiolitis." (PMID 27498757, 2016).
cryptococcal infection (7 papers, 2011 to 2023). "Uptake of C. neoformans leads to the recruitment of TLR9 to the fungal phagosome, and TLR9 KO mice were more susceptible to cryptococcal infection than WT control mice." (PMID 26903984, 2016). "With these markers of aggressive cryptococcosis, we can state that TLR9−/− mice are more susceptible to C. gattii, probably due to a mechanism associated with the decrease of a Th1 and Th17-type immune response that promotes the formation of titan cells in the lungs." (PMID 33446850, 2021). "Cryptococcal infection in TLR9 KO mice leads to decreased IFN-γ and TNF-α and an increase in IL-4 compared with WT mice." (PMID 26903984, 2016). "Our experimental findings suggest that IL-18R and TLR9 significantly contribute to MyD88-dependent host defense in cryptococcal infection." (PMID 22039448, 2011). "Because TLR9 reportedly plays a protective role in cryptococcal infection, we wanted to confirm its protective role in our infection model." (PMID 22039448, 2011). "Recent investigations have focused on the role of TLR9 in cryptococcal infection." (PMID 22039448, 2011). "In order to investigate the systemic cryptococcal infection, we evaluated C57BL/6 mice and C57BL/6 TLR9-/- after intratracheal infection with 104C. gattii yeasts for 21 days." (PMID 36145419, 2022). "Additionally, interplay between Toll-like receptor 9 (TLR9) and the CCL7/CCR2 axis is an important part of protective responses to lung cryptococcal infection." (PMID 29915688, 2018). "However, the impact of TLR9 on survival during cryptococcosis has not been described." (PMID 22039448, 2011).